ELK4 (ETS transcription factor ELK4)
Diseases named in the same sentence as ELK4 in open-access papers (continued):
Sharing a sentence is not in itself a finding about the gene and the disease.
cancer (28 papers, 2011 to 2025). A tumor composed of atypical neoplastic, often pleomorphic cells that invade other tissues. "ELK4, an Ets family transcription factor, exhibits diverse functions in cancer progression, typically acting as an oncogene that modulates processes such as angiogenesis, immune evasion, and metastasis." (PMID 41502523, 2025). "SLC45A3-ELK4 identified via RT-PCR occurs at a low level relative to wild-type ELK4 and acts as a lncRNA modulating cancer progression." (PMID 41155268, 2025). "Despite the coding capability of the ELK4 transcription factor moiety, SLC45A3–ELK4 fusion drives cancer cell proliferation primarily by acting as long non-coding chimeric RNA (lnccRNA)." (PMID 38919532, 2024). "Further analysis of these differential sites revealed the increased enrichment of motifs for other ETS TFs such as FLI1, ELK4 and ELK1, which have been implicated in cancer progression, following TWEAK-induced p52 activation." (PMID 37087499, 2023). "SLC45A3-ELK4 translates to the same protein as ELK4; however, the abundance of fusion RNA is less than 1% of wild-type ELK4 and regulates cancer cell proliferation as a lncRNA." (PMID 36527429, 2023). "For the LUAD network, four TFs, ETV1, ETV4, ETV6, and ELK4, were involved in the pathway called “transcriptional mis-regulation in cancer”." (PMID 35524179, 2022). "As a regulator of numerous proto-oncogenes, ELK4 is believed to regulate malignant transformation in the context of multiple cancer types." (PMID 32351540, 2020). "Many of the validated genes bound by ZNF322A such as HMGN5, GATA6, CCAR1 and ELK4, were found to be involved in tumorigenesis in other cancers, further supporting the oncogenic role of ZNF322A." (PMID 30258097, 2019). "ELK4 was reported to have crucial roles in a host of cancers." (PMID 33402177, 2021). "Primary cancer cells classified in C1 shared SNV clusters 18 and 15, including nonsynonymous mutations in transcription activator genes such as ELK4, KAT6B, and MAML3." (PMID 34507604, 2021). "Enrichment analysis was performed using HUGO symbols of genes recurrently hit per dataset, indicating that the pathway “Transcriptional misregulation in cancer [KEGG:05202]” was significantly more frequently hit (P = 1.6 × 10−4) within PCa due to TMPRSS2, ERG, ETV1, H3FA3, SLC45A3, and ELK4." (PMID 34891161, 2021). "In the cancer areas of samples 2.4 and 3.3 there are no spots with much higher expression of SLC45A3 than ELK4 (dark blue), hence no strong absence of the cis-SAGe is predicted in these areas." (PMID 32753032, 2020).
tumor (22 papers, 2011 to 2025). "Experiments in nude mice revealed that ELK4 silencing decreased tumor size, whereas MSI2 overexpression attenuated this inhibitory effect." (PMID 39969091, 2025). "ELK4 was identified as a key regulatory factor that markedly enhanced the proliferation, migratory capacity, and invasive potential of tumor cells, while changes in the TME were a driving force behind immune suppression and drug resistance." (PMID 40688093, 2025). "Cluster 0 expressed several tumour-related transcription factors such as ELK4, CREB1, cJun, JunD, KLF6, ETS-1 and ZNF217." (PMID 38480935, 2024). "Collectively, these data corroborate the crucial positive role of ELK4 in tumor angiogenesis in CRC." (PMID 37786278, 2023). "Of note, except for HOXA3, TWIST1, and ID1, the other seven genes are all proangiogenic genes that can be expressed and secreted by tumor cells, which implied the potential role of ELK4 in tumor angiogenesis in a paracrine manner in CRC." (PMID 37786278, 2023). "As expected, we found that the mutation of T361/T366/S381/S387A significantly abrogated the protumorigenic function of ELK4 in cell proliferation, cell migration, and tumor angiogenesis." (PMID 37786278, 2023). "Markedly increased tumor burdens in the lungs and liver were validated by hematoxylin and eosin (H&E) staining in mice injected with ELK4‐overexpressing cells, suggesting that overexpression of ELK4 enhances tumor metastasis in CRC." (PMID 37786278, 2023). "Taken together, these data suggest that overexpression of ELK4 can promote tumor growth and metastasis in CRC." (PMID 37786278, 2023). "In conclusion, we describe a new mechanism by which ELK4 promotes tumorigenesis and tumor progression in CRC." (PMID 37786278, 2023). "To further verify the ELK4‐LRG1 regulatory axis in vivo, we examined the expression of LRG1 in tumor tissues derived from wild‐type and Elk4−/− mice and from ELK4 OE/KD xenograft tumors." (PMID 37786278, 2023). "It was found that compared with sh-NC + oe-NC group, the volume and weight of transplanted tumor in sh-ELK4 + oe-NC group were reduced; compared with sh-ELK4 + oe-NC group, the tumor volume and weight were increased in sh-ELK4 + oe-KSR1 group." (PMID 34372882, 2021). "In accordance with SNHG22, ELK4 expression levels were significantly higher in GCs compared with non-tumor tissues in TCGA dataset." (PMID 34663788, 2021). "In summary, this study systematically elucidated the core mechanisms through which ELK4 mediated tumor progression, metabolic reprogramming, and immune evasion in C1 NDUFAB1+ subtype, offering crucial theoretical foundations for developing precision therapeutic strategies targeting this subtype." (PMID 40688093, 2025). "Moreover, the downregulation of ELK4 decreased Ki67 expression in tumor tissues, and the overexpression of MSI2 reversed this effect." (PMID 39969091, 2025). "Additionally, in vitro experiments confirmed that knockdown of ELK4 substantially curbed tumor cell proliferation, migration, and invasion." (PMID 40688093, 2025). "The proliferation of tumor cells was also dramatically reduced in Elk4−/− mice." (PMID 37786278, 2023). "Here, we showed that ELK4 promotes tumorigenesis and tumor progression in CRC in vitro and in vivo." (PMID 37786278, 2023). "ELK4 has been recognized as a promising target for treating multiple malignancies, as inhibiting its expression or activity can constrain the proliferation, migration, and immune evasion of tumor cells, while enhancing sensitivity to chemotherapy and immunotherapy." (PMID 40688093, 2025). "Given the numerous biological effects of TGF-β1 in regulating organ fibrosis, myogenesis, and tumor metastasis, our discovery of this ELK4-TGF-β1 axis could have broad implications and possibly enable new strategies to combat the anomalous responses induced by TGF-β1." (PMID 37853001, 2023).
tumor (continued). "Among these, the expression level of ELK4 was particularly prominent in C1 NDUFAB1+ subtype, significantly higher than in other tumor cell subtypes." (PMID 40688093, 2025). "ELK4 cooperates with SP1 and SP3 instead of SRF to transcriptionally regulate LRG1, among others, to promote tumor angiogenesis, tumor growth, and metastasis." (PMID 37786278, 2023). "The decrease in H2S promotes a positive immune tumor microenvironment in colorectal cancer by lowering ENO1 persulfidation in regulatory T cells and ELK4 in CD8+ T cells, thereby enhancing the activity of anti-PD-L1 and anti-CTLA4 therapies in colon cancer." (PMID 37381723, 2023). "Of note, we also observed a positive correlation between the tumor vasculature marker CD31 and the protein levels of LRG1, ELK4, SP1 and SP3 in our CRC cohort." (PMID 37786278, 2023). "Specifically, ELK4 has been shown to recruit and stabilize epigenetic regulator SIRT7 to promote tumor growth and maintain rapid cellular proliferation." (PMID 32351540, 2020). "Furthermore, we examined the expression levels of two tumor vasculature markers, CD31 and CD105, in xenograft tumors formed by CRC cells with stable knockdown or overexpression of ELK4 by IHC staining to confirm the role of ELK4 in tumor angiogenesis in vivo." (PMID 37786278, 2023). "Furthermore, the expression levels of AS-tDR-007333, HSPB1, ELK4, and MED29 in xenograft tumor tissues were significantly suppressed in the AS-tDR-007333-inhibitor group compared with that of NC and control groups." (PMID 35526007, 2022). "Indeed, ELK4 was found to be up-regulated in NSCLC cells and in NSCLC tissues and its expression levels were positively correlated with that of AS-tDR-007333 in NSCLC tumor tissues." (PMID 35526007, 2022). "Similarly, the fusion partner ELK4 is up-regulated in tumor samples expressing the SLC45A3-ELK4 fusion in comparison with fusion-negative tumor samples (p = 0.01) and benign samples (p = 6.3E-05, Wilcoxon rank-test)." (PMID 28467780, 2017).
infection (5 papers, 2014 to 2025). The state of being infected such as from the introduction of a foreign agent such as serum, vaccine, antigenic substance or organism. "Further studies have indicated that SRF utilizes MKL1/2 to fulfill steady-state cellular functions, including cytoskeletal organization, and utilizes ELK4 to facilitate acute responses to external infection." (PMID 41472164, 2025). "Intriguingly, ELK4 can regulate cellular homeostasis and stress responses in macrophages to affect acute responses to external infection." (PMID 34372882, 2021). "I conclude that SRF utilizes MKL1/2 to fulfill steady state cellular functions, including cytoskeletal organization, and utilizes ELK4 to facilitate acute responses to external infection." (PMID 24758171, 2014). "The overall view of the genome-wide locations of SRF, MKL1 and ELK4 has been constructed and the results suggest that SRF utilizes MKL1 to fulfill steady state cellular functions, including cytoskeletal organization, and utilizes ELK4 to facilitate acute responses to external infection." (PMID 24758171, 2014). "Intriguingly, it was unfolded that ELK4 could play an important role in regulating cellular homeostasis as well as stress responses in macrophages, thereby accelerating acute responses to external infection." (PMID 34372882, 2021). "Due to the lack of ChIP (chromatin immunoprecipitation)-grade ELK4 antibody and the technical difficulties of BMMC transfection and infection, we could not profile the DNA binding pattern of ELK4 in the mast cell system." (PMID 37529050, 2023). "Inactivation of Elk4 affected neither the CD8+ T-cell proliferative response nor the balance between SLECs and MPECs following infection." (PMID 39261466, 2024).
colorectal (1 paper, 2023). "Next, to explore the oncogenic role of ELK4 in CRC tumorigenesis, we established a model of azoxymethane‐dextran sodium sulfate (AOM‐DSS)‐induced colorectal tumorigenesis in wild‐type and Elk4−/− mice." (PMID 37786278, 2023).
immune disorders (1 paper, 2024). "While some of these regulatory factors (e.g., NFKB, STAT, and IFN) have been reported as shared TFs enriched in inflammatory fibroblasts across a diverse group of immune disorders, others displayed distinctive TFs (e.g., FOSL2, JUN, and ELK4) unique to inflammatory keratocytes." (PMID 39677756, 2024).
ELK4 also shares sentences with these, for which no sentence is quoted: sarcoma (2 papers); bladder carcinoma (1); cervical tumor (1); chondrosarcoma (1); clear cell renal cell carcinoma (1); colorectal tumor (1); COVID-19 (1); head and neck cancer (1); ischemic cardiomyopathy (1); lymphoma (1); metastatic disease (1); muscle atrophy (1); myeloid malignancies (1); neurodegenerative disease (1); non-small cell lung carcinoma (1); ovarian tumor (1); pancreatic cancer (1); skin cancer (1); skin cutaneous melanoma (1); teratocarcinoma (1); thyroid cancer (1).